ELOA (elongin A)
Description:
SIII, also known as elongin, is a general transcription elongation factor that increases the RNA polymerase II transcription elongation past template-encoded arresting sites. Subunit A is transcriptionally active and its transcription activity is strongly enhanced by binding to the dimeric complex of the SIII regulatory subunits B and C (elongin BC complex). As part of a multisubunit complex composed of elongin BC complex (ELOB and ELOC), elongin A/ELOA, RBX1 and CUL5; polyubiquitinates monoubiquitinated POLR2A.
Synonyms: TCEB3; SIII; TCEB3A; ELOA1; SIII p110
Tractability: PROTAC: ubiquitination databases record sites on it.
Gene: Protein-coding gene on chromosome 1 (23,743,448 to 23,762,059, forward strand). Ensembl gene ENSG00000011007.
Subcellular location: Nucleus
Subcellular location (Human Protein Atlas): Nuclear speckles; Cytosol
Pathways (Reactome):
Disease: Formation of HIV elongation complex in the absence of HIV Tat; Formation of HIV-1 elongation complex containing HIV-1 Tat; HIV elongation arrest and recovery; Pausing and recovery of HIV elongation; Pausing and recovery of Tat-mediated HIV elongation; Tat-mediated HIV elongation arrest and recovery; Tat-mediated elongation of the HIV-1 transcript
Gene expression (Transcription): Formation of RNA Pol II elongation complex; RNA Polymerase II Pre-transcription Events; RNA Polymerase II Transcription Elongation
Gene Ontology:
Molecular function: protein binding
Biological process: transcription initiation at RNA polymerase II promoter; regulation of transcription by RNA polymerase II; regulation of DNA-templated transcription; transcription by RNA polymerase II; transcription elongation by RNA polymerase II
Cellular component: elongin complex; extracellular region; nuclear speck; nucleus; nucleoplasm; site of DNA damage
Genetic constraint (gnomAD): Loss-of-function variants: 14 observed, 76.86 expected, observed/expected ratio (o/e) 0.18, 90% interval 0.12 to 0.28. The upper end of that interval is the gene's LOEUF score, 0.28, which puts it in group 1 of 6, group 1 being the genes least tolerant of losing a copy. Missense variants: 752 observed, 932.4 expected, observed/expected ratio (o/e) 0.81, 90% interval 0.76 to 0.86. Synonymous variants: 340 observed, 355.6 expected, observed/expected ratio (o/e) 0.96, 90% interval 0.87 to 1.05.
Homologues: Orthologues: chimpanzee ELOA (99% identical), macaque ELOA (96% identical), rat Eloa (83% identical), mouse Eloa (83% identical), guinea pig ELOA (80% identical), tropical clawed frog eloa (48% identical), Drosophila melanogaster EloA (24% identical), zebrafish eloa (24% identical), Caenorhabditis elegans tceb-3 (16% identical). Paralogues in human: ELOA2 (48% identical).
Diseases named in the same sentence as ELOA in open-access papers:
ELOA is named in the same sentence as 19 diseases in open-access papers, as found by Europe PMC text mining. Sharing a sentence is not in itself a finding about the gene and the disease. The quoted sentences say what the papers report.
colorectal cancer (3 papers, 2022 to 2024). A primary or metastatic malignant neoplasm that affects the colon or rectum. "Elongin A (ELOA), our previous work revealed, serves as a novel tumor suppressor in colorectal cancer." (PMID 37694492, 2023).
cervical cancer (2 papers, 2022 to 2023). A primary or metastatic malignant neoplasm involving the cervix. "Little is known about the protein encoded by the REXO1 gene, other than its participation in RNA polymerase II transcription via Elongin A and its role promoting cervical cancer cell proliferation and progression." (PMID 35033200, 2022). "Interestingly, a recent study reported that miR‐140‐3p targets ELOA in cervical cancer, and whether this regulation also exist in GC cells remains to be elucidated." (PMID 37694492, 2023). "Interestingly, a recent study reported that ELOA promotes the progression of cervical cancer." (PMID 37694492, 2023).
esophageal cancer (2 papers, 2023 to 2025). A primary or metastatic malignant neoplasm involving the esophagus. "In another study, a subtype of signature composed of ELOA and SCAF4 was identified, and a subtype diagnostic and prognostic model was constructed for therapeutic targeting in esophageal cancer." (PMID 40149317, 2025).
cleft lip and (1 paper, 2018). "The LOC421892 gene is a homolog of TCEB3 (also known as ELOA) gene, which is related to von Hippel-Lindan (VHL) and nonsyndromic cleft lip and palate (NSCLP) in human." (PMID 29954329, 2018).
Cockayne syndrome (1 paper, 2017). A multisystem condition characterized by short stature, a characteristic facial appearance, premature aging, photosensitivity, progressive neurological dysfunction, and intellectual deficit. "In this study, we demonstrate (i) that Elongin A and the ubiquitin ligase subunit CUL5 associate in cells with the Cockayne syndrome B (CSB) protein and (ii) that this interaction is also induced by DNA-damaging agents and α-amanitin." (PMID 28292928, 2017).
colon cancer (1 paper, 2021). "We performed CUT&RUN in DLD1, a human colon cancer cell line, with anti–Elongin A antibody and immunoglobulin G (IgG) controls." (PMID 33298525, 2021).
gastric cancer (1 paper, 2023). A primary or metastatic malignant neoplasm involving the stomach. "However, the function and mechanism of ELOA in other cancer types, including gastric cancer (GC), remain to be elucidated." (PMID 37694492, 2023).
Ogden syndrome (1 paper, 2025). Ogden syndrome is a rare, genetic progeroid syndrome characterized by a variable phenotype including postnatal growth delay, severe global developmental delay, hypotonia, non-specific dysmorphic facies with aged appearance and cryptorchidism, as well as cardiac arrthymias and skeletal anomalies. "Combined analyses of Ogden syndrome cellular models and HeLa cancer models identified a subset of common N-terminally acetylated proteins, including GCN1, ELOA, PPIA, RPL13A, RPP30, and SAE1." (PMID 40558489, 2025).
ovarian carcinoma (1 paper, 2020). A malignant neoplasm originating from the surface ovarian epithelium. "It has been reported that CYP26A1, MTRNR2L1, ELOA, and FAM53A were all related with ovarian carcinomas, and CYP26A1 may acts as a meiosis-inhibiting factor and related with the gonadal retinoic acid-degradation." (PMID 32425983, 2020).
Sepsis (1 paper, 2022). Sepsis is defined as life-threatening organ dysfunction caused by a dysregulated host response to infection. "SRP14, which traffics secretory proteins through the endoplasmic reticulum, and ELOA, a subunit of the transcription factor B (SIII) complex, may aid protein synthesis by immune cells during sepsis." (PMID 36572854, 2022).
tumor (5 papers, 2017 to 2025). "For instance, in tumor cells, high ELOA expression can promote cell proliferation and migration, thereby enhancing tumor aggressiveness and metastatic potential." (PMID 41268559, 2025). "To further evaluate the proliferation‐regulatory function of ELOA in‐vivo, we constructed a tumor xenograft model using MKN45 cells with stable knockdown of ELOA." (PMID 37694492, 2023). "In conclusion, we revealed that ELOA promotes GC tumor growth and metastasis by transcriptionally activating RBP1." (PMID 37694492, 2023). "Correlation analyses showed that ELOA expression was correlated with tumor stage and lymph node metastasis." (PMID 37694492, 2023). "Enhanced ELOA expression in GC tissues was obviously correlated with poor tumor differentiation, lymph node metastasis, advanced tumor stage, and a poor prognosis." (PMID 37694492, 2023). "In this study, we identified that RBP1 is a direct downstream gene of ELOA, and mediates its tumor‐promoting functions in GC." (PMID 37694492, 2023). "MiR‐490‐3p, a tumor suppressive miRNA in GC,18, 19 was identified as a key miRNA inhibiting ELOA in GC." (PMID 37694492, 2023). "Of them, only LHPP, a newly discovered tumor suppressor, appeared to be upregulated by ELOA and was selected for further validations." (PMID 36376892, 2022). "The results indicated that silencing ELOA expression slowed down tumor growth." (PMID 37694492, 2023). "Correlation analyses showed that ELOA expression levels were correlated with tumor stage." (PMID 36376892, 2022). "Furthermore, specific knockdown of RBP1 reduced the tumor‐promoting ability of ELOA in GC cells." (PMID 37694492, 2023). "Interestingly, we recently revealed that ELOA was downregulated in CRC and inhibited CRC progression by activating the transcription of LHPP, a putative tumor suppressor." (PMID 37694492, 2023). "Our previous work showed that ELOA is downregulated in CRC and suppresses tumor progression." (PMID 37694492, 2023). "Subsequent experimental validations confirmed the increased ELOA protein expression in GC tissues, and obviously enhanced ELOA staining was observed in 77% tumor tissues compared with paired nontumor tissues." (PMID 37694492, 2023). "What is more, the tumor-promoting effects of DLGAP1-AS2 by inhibiting ELOA were observed in WT but not in Trim21-KO CRC cells." (PMID 36376892, 2022). "We reveled ELOA as a novel transcription regulator for LHPP, a newly identified tumor suppressor." (PMID 36376892, 2022).
cancer (3 papers, 2022 to 2025). A tumor composed of atypical neoplastic, often pleomorphic cells that invade other tissues. "Together, these data indicate that ELOA exerts cancer‐promoting effects by regulating RBP1 in GC." (PMID 37694492, 2023). "Little is known about the downstream targets of ELOA in cancer cells." (PMID 36376892, 2022). "However, how the ELOA/RBP1 axis regulates GC progression exactly remains to be elucidated, and whether this regulatory mechanism works in other cancer types also remains to be revealed." (PMID 37694492, 2023).
infection (1 paper, 2020). The state of being infected such as from the introduction of a foreign agent such as serum, vaccine, antigenic substance or organism. "The subcellular distribution of elongin A and B, in contrast, remained unchanged by infection, although α-amanitin had an influence on Elongin A distribution." (PMID 31941775, 2020).
ELOA also shares sentences with these, for which no sentence is quoted: Diamond-Blackfan anemia (1 paper); lymphoma (1); malaria (1); myeloma (1); neurological disease (1); rectal cancer (1).